MYC (MYC proto-oncogene, bHLH transcription factor)
Diseases named in the same sentence as MYC in open-access papers (continued):
Sharing a sentence is not in itself a finding about the gene and the disease.
tumor (continued). "Upstream analysis of the genes involved in the tumor-correlated cluster (N = 283) did identify MYC as an upstream transcriptional regulator (Right-tailed Fisher’s Exact Test p-value = 6 × 10− 3), even though MYC and 2-HG are not differentially associated." (PMID 29506475, 2018). "However, super-enhancer activity is also important in non MYC-driven tumours." (PMID 29759978, 2018). "Furthermore, these tumor cells also express substantially more MYC protein in their nucleus." (PMID 30223484, 2018). "The same molecular cascade from GCN5 to MYC might be activated in tumor cells." (PMID 29555684, 2018). "Taken together with the identification of EGFR and MYC amplification in cold tumours, our analysis suggests that pharmacological inhibition of EGFR/mTORC1/MYC-driven glycolysis could be an effective means by which to ‘warm-up’ these tumours and potentially enhance responses to ICB." (PMID 30104673, 2018). "However, if the tumor were resistant to chemotherapy, it may be possible to acquire c-MYC amplification or copy number gain during neoadjuvant chemotherapy." (PMID 30420657, 2018). "Moreover, the levels of the lipid peroxidation product malondialdehyde (MDA), which was used as a presumptive measure of the ROS levels, were higher in both the THP-1 vector and THP-1 c-MYC tumor tissues following tetrandrine treatment than in those treated with vehicle." (PMID 29700286, 2018). "Abnormal activation of the MYC oncogene may occur through several distinct mechanisms and it is currently recognized as a major event in many cellular pathways leading to the development of various types of neoplasia, including PCa23." (PMID 29415999, 2018). "Thus, given the putative tumor suppressor activity of HBD1, the delicate balance of the regulation of HBD1 gene expression exerted by MYC may play a key role in determining the fate of cancer cells and tumor progression." (PMID 30575780, 2018). "Since senescence and apoptosis are the two main barriers against tumor development, cooperativity between MYC and RAS in senescence and apoptosis suppression may thus constitute one of the major mechanisms behind the transformation of rodent cells by these oncogenes." (PMID 30526305, 2018). "In addition to human studies correlating elevated MYC levels with worse clinical outcomes, disease progression, and metastasis, in animal models, spontaneous metastatic spread and rapid tumor progression is observed in KRAS mutant tumors with exogenous MYC62,63." (PMID 30013058, 2018). "Moreover, although WNT signaling is activated by APC mutations in FAP neoplasms, reduced inactivation of OTX2 and activation of MYC may contribute to tumor development in FAP." (PMID 30220972, 2018). "Given that KRAS and MYC are currently therapeutically undruggable genetic alterations found in many tumor types, a greater understanding of the interaction and cooperativity between these oncogenic changes and GATAD2B may open up the exploration of new therapeutic approaches." (PMID 30013058, 2018). "Specifically, the cancer phenotypes could arise when XPB-dependent DNA repair defects alter hyperproliferative input(s); e.g., defective function of the FUBP1/FIR/TFIIH nexus would be predicted to disrupt repression of the MYC oncogene and contribute to XP-related neoplasia." (PMID 28398229, 2017). "Likewise, MYC was predicted to be negative regulator of tumor immunity." (PMID 29051489, 2017).
tumor (continued). "Thus, via control of both glycolysis and glutaminolysis, MYC functions as an essential regulator of cancer cell metabolism, allowing for tumor cells to meet their metabolic needs depending on the availability of glucose and/or glutamine as a substrate for glycolysis or oxidative phosphorylation." (PMID 28362357, 2017). "Xenografts replicated the phenotype of the primary tumour, including high degree of clustering in DNA methylation analysis, high proliferation, expression of tumour markers, MYC amplification and elevated MYC expression, and sensitivity to the MYC inhibitor JQ1." (PMID 28417956, 2017). "However, how DNA methylation contributes to MYC-driven tumor maintenance, and how genome-wide aberrant DNA methylation patterns are established and maintained remains largely unknown." (PMID 29100357, 2017). "However, in cancer, MYC expression and/or activity are frequently co-opted by the tumor, resulting in elevated MYC RNA and protein expression; accordingly, MYC has been identified as one of the most commonly deregulated oncogenes in a wide variety of cancer types." (PMID 28587062, 2017). "Hence, MYC binds diverse DNA motifs with a broad range of affinities in a sequence-specific and dose-dependent manner, suggesting that MYC overexpression has more selective effects on the tumor transcriptome than previously thought." (PMID 28719624, 2017). "Thus, low c-MYC expression levels lead to increased proliferation and activation of CSCs, including the expression of markers associated with reprogramming (e.g., NANOG, OCT4 and EpCAM), expansion of side populations and acceleration of tumor growth." (PMID 28422055, 2017). "These latter observations suggest that MMCC, further to promote the expansion of c-MYC-expressing tumour cells at the expense of the surrounding stromal cells, may shape human tumour microevolution through constant culling of cells with the lowest c-MYC activity in the field." (PMID 28974715, 2017). "Thus, targeting MYC to decrease ductal-neuroendocrine lineage plasticity in PDA cells may increase tumor cell response to standard-of-care gemcitabine." (PMID 29170413, 2017). "Nadroparin, a MYC inhibitor, may inhibit tumor progression (Nagy, Turcsik & Blaskó, 2009)." (PMID 37133296, 2017). "Additionally, tools such as nanoproteomic assays might be developed using the NanoPro 1000 to monitor signaling and MYC target gene expression in rare tumor cell populations." (PMID 28362357, 2017). "At the broadest level, global amplification as a result of elevated MYC levels will increase the output of previously active transcriptional programs, potentiating the growth and proliferation programs already operational in developing organs, proliferating cell culture systems or tumours." (PMID 28398229, 2017). "Nonetheless, what causes MYC to be overexpressed in tumours and not in cell lines?" (PMID 28619028, 2017). "Interestingly, this dependency of BL tumours on tonic BCR signalling may explain why, even though one Ig allele is involved in the c-MYC translocation, all BLs retain surface Ig expression from a second functionally rearranged allele." (PMID 28893938, 2017). "To determine if MYC family proteins could cooperate with MCPyV IMR90 cells, we treated cells stably expressing ST, GFP, or p53DD + hTERT (PH) and MCPyV tumor-derived early-region (PHE) with inducible expression of MYC, MYCN or MYCL with dox for 48 hours and immunoblotted for HK2, MCT1 and LDHA." (PMID 27880818, 2016). "Notably, tumor suppressive activities of E2F2 have been reported in MYC triggered tumorigenesis." (PMID 27081696, 2016).
tumor (continued). "Thus, the tumor-suppressive action of NDRG2 may be attributed to its ability to compromise MYC-driven metabolic reprogramming in cancer cells." (PMID 27447861, 2016). "c-MYC protein overexpression was associated with non-aggressive characteristics, including early pT stage, low-grade differentiation, absence of perineural invasion, and smaller tumor size (P < 0.001, P = 0.007, P = 0.025 and P < 0.001, respectively)." (PMID 27619912, 2016). "Moreover, the role of MYC proteins as transcriptional amplifiers has been suggested by studies demonstrating that MYC overexpression increases the total amount of RNAs both in tumor cells as well as in physiological settings." (PMID 27769070, 2016). "Thus, MYC significantly co-localizes with active β-catenin in a very small number of tumor cells." (PMID 27821172, 2016). "Moreover, MYC has been shown to increase hnRNPA1 expression leading in turn to higher expressing of pyruvate kinase, contributing to aerobic glycolysis frequently observed in tumor cells." (PMID 27303665, 2016). "However, to survive and evolve in a hypoxic tumor milieu, cancer cells must revise MYC-driven metabolism because the mitochondrial respiratory chain provides free electrons to generate oxygen free radicals with inefficient production of ATP due to oxygen depletion." (PMID 27447861, 2016). "To evaluate whether the transgenic or transplant versions of the Vk*MYC mouse model would replicate our clinical findings, we examined a cohort of aged transgenic Vk*MYC mice with spontaneous onset tumours and two of the more commonly used transplant clones in our laboratory: Vk#4929 and Vk#31." (PMID 27599546, 2016). "Moreover, MLLT1-mutant tumours show an increase in MYC gene expression and HOX dysregulation." (PMID 26635203, 2015). "The MYC abnormality may act as the accomplice to the tumour transformation and aggressive behavior." (PMID 26517511, 2015). "Hence, MYC inactivation could lead to the direct change in expression of cytokines by tumor cells, thereby recruiting immune cells." (PMID 25089198, 2014). "Therefore, MIBG and phenformin can be tumor-targeting MYC/MYCN destabilizing agents in NB." (PMID 24190252, 2014). "In these tumor conditions, exclusive MYC targeting is insufficient because each population exhibits different metabolic conditions; however, by targeting general transcription, highly expressed genes, such as MYC and HIF, can be repressed in various cell populations." (PMID 24576043, 2014). "Furthermore, our results suggest that inhibition of AP4 function, e.g. by small molecules blocking AP4 homodimerization, may be employed to therapeutically target c-MYC-driven tumor cells." (PMID 25261373, 2014). "We speculate that miR-27a and miR-24 may serve at a ‘standby state’, which means they are ready for the manipulation by different cellular factors, as GATA-1 in erythropoiesis, c-MYC in tumour metastasis, Runx2 in osteoblast differentiation and PU.1 in B-cell development." (PMID 24049083, 2014). "Thus, MYC degradation by FBXW7 may not only induce a state of tumor dormancy but could also have an anti-tumor effect." (PMID 24053468, 2013). "Therefore, our study provides first proof of principle that immunologically targeting c-MYC may result in anti-tumor activity." (PMID 24130880, 2013). "One major question regarding this strategy is, whether there is a therapeutic window in which c-MYC specific T cells eliminate all tumor cells but do not cause fatal damage to healthy tissue." (PMID 22860051, 2012).
tumor (continued). "Likewise, when we assessed MYC staining in an independent cohort of 21 cases of secondary DLBCL, we found that all MYC translocation positive cases had >50% MYC positive tumor nuclei and that an additional two cases of secondary DLBCL without a MYC translocation also had increased MYC expression." (PMID 22511926, 2012). "Members of the let-7 family play a major role in cell differentiation and are considered to act as tumor suppressors by silencing numerous genes that encode oncogenic proteins including HMGA2, insulin-like growth factor 2-binding protein 1 (IGF2BP1), RAS and c-MYC." (PMID 21853155, 2011). "Interestingly, gain of MYC was more common in non-C5 tumours (p<0.01)." (PMID 21533284, 2011). "Finally, there is a growing body of evidence that deregulation of translational control may be a common mechanism by which oncogenic pathways promote tumour initiation and progression (e.g., MYC and RAS)." (PMID 21772331, 2011). "These negative results may be due to the fact that loss of RB may not strongly modify the tumor phenotype of MYC-expressing mice in our model." (PMID 21573126, 2011). "Thus, whether MYC induces reversible tumorigenesis alone is dependent upon the specific tumor context." (PMID 18461184, 2008). "We acknowledge that the differences seen between tumor initiation and maintenance could be secondary to differences in the expression of MYC and K-ras from the two different tissue specific promoters and/or may be confined to the particular genetic background of the mice used in our study." (PMID 18461184, 2008). "Interestingly, MYC immunostaining decreased with tumour progression." (PMID 17146477, 2007). "Therefore, if MYC is downregulated during tumour progression as was observed in the present study, this might reflect a mechanism to inhibit MYC-activated apoptosis." (PMID 17146477, 2007). "RSPO4 also induced significant suppression of the transcriptional activities of critical Wnt/β-catenin target genes CCND1, c-MYC and MMP7, which play important roles in tumor cell metastasis." (PMID 41522353, 2026). "The mechanistic basis involves ARMC12, which functions within liquid-liquid phase-separated condensates to co-activate MYC, driving the subsequent up-regulation of NUP62, NUP93, and NUP98, elevation of NPC number, and tumor progression." (PMID 41510169, 2026). "This epigenetic change inhibits the TOM121/MYC/PD-L1 axis, leading to reduced PD-L1 expression and a consequent enhancement of CD8+ T cell-mediated tumor killing." (PMID 41522342, 2026). "c-MYC and EZH2 expression was assessed immunohistochemically in tumor samples and evaluated by nuclear staining intensity and the percentage of stained tumor cells." (PMID 41928013, 2026). "miR-192-5p facilitates proliferation by repressing the proapoptotic factor BIM; miR-223-3p enhances tumor growth by directly targeting FBXW7, a tumor suppressor that controls the stability of key cell cycle regulators such as c-MYC and c-Jun." (PMID 41596525, 2026). "In particular, FISH assays performed on tumor sections highlighted that KHSRP, even in the complexity of an in vivo model, maintains its ability to localize within the sequences of c‐KIT and c‐MYC, further underscoring the biological relevance of our findings." (PMID 39763191, 2025). "Its advantage lies in effectively inhibiting MYC and Bcl-2 mediated cell proliferation and anti-apoptotic signals, making it particularly suitable for DEL patients with high tumor burden (elevated LDH), as in the present case." (PMID 41229502, 2025).
tumor (continued). "To understand the clonal genetic events in tumour initiation, evolution and progression, we molecularly profiled a specific tumour cohort with a known amplification of MYCN or MYC or overexpression of PRDM6 (n = 16 primary, n = 4 relapses)." (PMID 40335697, 2025). "By mediating c-MYC degradation, FBXW7 disrupts the signaling pathways that drive M2 polarization, thereby suppressing the tumor-promoting functions of these macrophages." (PMID 40534867, 2025). "In the MNA-NB mouse model, the compound can downregulate MYC/MYCN expression, induce apoptosis, and inhibit tumor growth with low toxicity." (PMID 41244073, 2025). "In DLBCL, expression of miR-665 can suppress tumor progression by targeting and inhibiting LIM and SH3 domain protein 1 (LASP1) and MYC, both essential for invasion, migration, and cell proliferation." (PMID 40255571, 2025). "By demonstrating that disruption of PA2G4 impairs MYC stability and tumor cell viability, we provide a compelling rationale for targeting the PA2G4–MYC axis as an alternative to direct MYC inhibition." (PMID 41002386, 2025). "To address this, we use MYC inhibitors, such as I-BET726 and JQ1, which enhance tumor antigen presentation and immune activation." (PMID 40552293, 2025). "Immunohistochemistry (IHC) staining and western blotting of tumor xenografts 5 days post treatment confirmed significant downregulation of p300/CBP, AR, PSA, MYC, Ki67, CCND1, NKX3-1, CITED2, H3K27ac and H2BK20ac." (PMID 41044247, 2025). "EZH2 interacts with oncogenes (MYC, PTEN) to influence tumor malignancy by activating the EMT mechanism, initiating GBM cell invasion and metastasis." (PMID 40725030, 2025). "The small molecule MYC inhibitor (MYCi975) that disrupts MYC/MAX dimers and induces MYC degradation in diverse tumor cell lines likewise reduced cell viability of WT cultures, with organoids being most sensitive." (PMID 39740515, 2025). "Co‐immunoprecipitation (co‐IP) experiments demonstrated physical bonding between MYC and FOSL2 in M‐M2 tumor cells." (PMID 39899538, 2025). "This indicates that the overexpression of NCL leads to the relief of MYC-mediated transcriptional inhibition of TXNIP, thereby promoting tumor growth in vivo." (PMID 40346484, 2025). "ecDNA amplifications that harbor driver oncogenes such as EGFR, MYC, MDM2, and CDK4 were detected in 17.1% of 39 human tumor subtypes, including GBM24." (PMID 40678238, 2025). "Together, our results indicate that STM2457 enhances anti-tumor effects of venetoclax by decreasing the expression of both MCL1 and MYC." (PMID 40169588, 2025). "Heatmap clustering of subtype-specific and oncogenic-pathway-related genes revealed that PDTOs from patients 1 and 2 closely mirrored their tumor tissues, particularly in the expression of CDK4, MDM2, and myelocytomatosis oncogene (MYC)." (PMID 41376821, 2025). "Low levels of KLF4, c-MYC, and NANOG and high expressions of SOX2 and OCT4 in tumor tissue correlated with poor overall survival (OS) and disease-free survival (DFS), respectively." (PMID 41463190, 2025). "The down-regulation of miR-375-3p levels in SCLC will lead to increased expression of target genes (such as MYC and MCL1), promoting the proliferation and survival of tumor cells." (PMID 40332288, 2025).